IL1B (interleukin 1 beta)
Diseases named in the same sentence as IL1B in open-access papers (continued):
Sharing a sentence is not in itself a finding about the gene and the disease.
malaria (continued). "However, excessive IL-1β secretion can be deleterious to the host; in fact, we observed that higher production of IL-1β correlates with early death in murine experimental malaria." (PMID 19696895, 2009). "Corroborating this hypothesis, we showed that IL-1β- and NLRP3- deficient mice showed a better survival than wild type mice in murine experimental model of malaria." (PMID 19696895, 2009). "Genotype frequencies did not deviate from predictions of the Hardy-Weinberg equilibrium either in IL1B -31C>T (for mild malaria patients, P = 0.58; for cerebral malaria patients, P = 0.44) or in IL1RA VNTR (for mild malaria patients, P = 0.27; for cerebral malaria patients, P = 0.73)." (PMID 16098232, 2005). "Furthermore, the increased serum concentration of IL-1β could also be a contributing factor to the mechanical antinociception and thermal hyperalgesia observed in mice with tumors and healed of malaria." (PMID 38774541, 2024). "This somewhat variable picture suggests an uncertain role for monocytes in malaria pathology, but with the accumulation of monocytes at IE sequestration sites in the brain microvascular, IE-induced generation of IL-1β or other soluble factors could lead to elevated local concentrations." (PMID 37141324, 2023). "However, reports on the effect of IL-1β on malaria severity are inconsistent." (PMID 36309676, 2022). "The allelic analysis showed that carriage of the mutant allele A in IL-1β rs1143634 SNP (AOR: 0.66, 95%CI 0.46–0.97; P = 0.032) and mutated allele A in FcγRIIA/CD32 rs1801274 SNP (AOR: 0.68; 95%CI 0.52–0.89; P = 0.005) were associated with protection from clinical malaria." (PMID 33593344, 2021). "We previously found in longitudinal analyses of Malian children that Pf-iRBC-inducible production of IL-1β and IL-6 by monocytes was lower 7 days after treatment of febrile malaria relative to that induced at the pre-infection baseline before the six-month malaria season." (PMID 33822828, 2021). "Because IL-1β and IL-6 are primarily produced by monocytes/macrophages, we isolated monocytes/macrophages from 9 additional children who had PBMCs available at their healthy baseline before the malaria season and 14 days after their first febrile malaria episode of the ensuing malaria season." (PMID 24743880, 2014). "It has been also shown that cytokines play an important role in the immunopathology of malaria and many field studies have described an association of specific cytokines with severity of disease, in particular IL-2, IL-12, IFN-γ, IL-1β, IL-6, TNF, IL-4, IL-10, MIP-1β, and TGF-β." (PMID 22280502, 2012). "Furthermore, the absence of NLRP3 or IL-1β augmented survival to malaria caused by P. chabaudi adami DS." (PMID 19696895, 2009). "If the increased expression of IL-1B observed in brain of cerebral malaria patients is due to the increased transcription of IL1B caused by the IL1B -31T allele, the frequency of IL1B -31T should be higher in cerebral malaria patients than in mild malaria patients." (PMID 16098232, 2005). "On admission, the concentrations of IL-1β (p = 0.0026), IL-2 (p < 0.0001), IL-6 (p = 0.0009), TNF-α (p > 0.0001), and IFN-γ (p > 0.0001) were significantly upregulated in patients with malaria and typhoid comorbidity, comparing to healthy controls." (PMID 40014608, 2025). "For example, IL-1β can synergize with IL-1α and TNF-α to enhance nitric oxide (NO) and IFN-γ production in murine malaria models." (PMID 40980010, 2025). "In our current investigation, we assessed the levels of IL-1β and TNF-α, two key players in the pathophysiologic aspects of cancer and malaria, particularly inflammation and pain." (PMID 38774541, 2024). "The intense sequestration exacerbates the inflammatory response and cause cytokine storm, especially increasing IL‐10, GM‐CSF, IL‐6, IL‐1β, IFN‐ɣ, and TNF‐α levels, which promotes the progression of severe malaria." (PMID 39240033, 2024).
malaria (continued). "Severe malarial anemic children had elevated TNF‐α (p < .001), IFN‐ɣ (p < .001), IL‐1β (p < .001), IL‐6 (p < .001), GM‐CSF (p < .001), and IL‐10 (p < .001), but lower IL‐3 (p < .001) and TGF‐β (p < .001) than those with uncomplicated malaria." (PMID 39240033, 2024). "Malaria‐infected children had relatively higher TNF‐α (p < .001), IFN‐ɣ (p < .001), IL‐1β (p < .001), IL‐6 (p < .001), GM‐CSF (p < .001), and IL‐10 (p < .001) levels than uninfected participants." (PMID 39240033, 2024). "Severe malaria patients have been found to produce high levels of systemic proinflammatory cytokines such as IFN-γ, IL-1β, IL-6, and TNF-α." (PMID 38787228, 2024). "IFN-γ, IL-2, IL-5, IL-6, and IL-12 were increased in mild malaria, whereas TGF-β, TNF, IL-10, and IL-1β were particularly elevated in cerebral malaria." (PMID 38774541, 2024). "In the current study, participants with malaria had higher TNF‐α/IL‐10, TNF‐α/TGF‐β, IFN‐ɣ/TGF‐β, and IL‐1β/TGF‐β, but lower IFN‐ɣ/IL‐10, IL‐1β/IL‐10, and IL‐6/TGF‐β ratios than those in the control group." (PMID 39240033, 2024). "Participants with malaria had higher TNF‐α/IL‐10, TNF‐α/TGF‐β, IFN‐ɣ/TGF‐β, IL‐1β/TGF‐β and, but lower IFN‐ɣ/IL‐10, IL‐1β/IL‐10, and IL‐6/TGF‐β ratios than those in the control group." (PMID 39240033, 2024). "Malaria presents with enhanced release of TNF‐α, IFN‐ɣ, IL‐1β, IL‐6, GM‐CSF, and IL‐10, but downregulates IL‐3 and TGF‐β in Ghanaian children." (PMID 39240033, 2024). "Elevated levels of pro-inflammatory cytokines such as TNF-α, IL-1β, and IFN-γ are typically observed in uncomplicated malaria." (PMID 38694310, 2024). "The choice of cytokines and chemokines measured was based on their reported implication in severe malaria (i.e. IFNγ, TNF-α, IL6, IL-1β, RANTES, MIP-1, MCP-1, IP10)." (PMID 37350957, 2023). "For instance, increased levels of IL-12, IL-6, IL-10, IL-1β and IFN-γ have been identified during severe malaria whereas low levels of 1L-12p70, IL-10, IFN-α, and IFN-γ have been associated with SM in children." (PMID 37525227, 2023). "Increased levels of proinflammatory cytokines such as interleukin-1 beta (IL-1β), IL-6, IL-8, IL-10, IL-12, IL-13, IL-31, IL-33, and tumor necrosis factor alpha (TNF-α) have been reported to be related to clinical malaria or severe malaria." (PMID 35396564, 2022). "In the Mali cohort we found that monocytes of adults produced lower levels of the inflammatory cytokines IL-1β, IL-6 and TNF in response to Pf-iRBC stimulation compared to monocytes of infants and children, or malaria-naïve U.S. adults." (PMID 33822828, 2021). "Significantly lower cytokine responses (IL-1β, IL-6, IL-10, TNF-α and IFN-γ) to LPS and Staphylococcus aureus were observed among participants with asymptomatic malaria compared to controls." (PMID 34177883, 2021). "Production of pro-inflammatory cytokines and chemokines such as IL-1β, IL-6, IL-8, IL-12, IFN-γ, and TNF induce fever and other signs and symptoms in previously unexposed individuals resulting in severe and fatal malaria." (PMID 33746974, 2021). "We found that monocytes of Malian adults produced lower levels of the inflammatory cytokines IL-1β, IL-6 and TNF in response to Pf-iRBC stimulation compared to monocytes of Malian infants and children or malaria-naïve U.S. adults." (PMID 33822828, 2021). "Another study in India has recently shown that women with Pv malaria in pregnancy have more IL-6, TNF and IL-1β in peripheral plasma than uninfected pregnant women." (PMID 32365058, 2020). "In women with Malaria+CHB, Levels of 3 out of the 6 pro-inflammatory cytokines negatively correlated with malaria parasitemia [IL-1β (P<0." (PMID 31002731, 2019). "In order to demonstrate the role of cytokines in the modulation of HAT progression, we assayed six cytokines (IFN-γ, IL1-β, TNF-α, IL-6, TGF-β and IL-10) in plasma of both cases (N = 49, after excluding 6 malaria co-infected patients) and controls (N = 41)." (PMID 26090964, 2015).
malaria (continued). "As observed in the rodent malaria model, IFN-γ-priming of primary human monocytes mimics in vivo infection with Plasmodium and augments expression of pro-caspase-1, pro-IL-1β as well as IL-1β release induced by LPS stimulation." (PMID 24453977, 2014). "In both malaria and coinfected groups the median levels of TNF-α, IL-2, IL-10, IL1-β, MCP-1, and IL-6 were observed to be mostly significantly increased compared with those intestinal parasites and uninfected groups (P < 0.001 for all comparisons)." (PMID 25309052, 2014). "Previous studies on the impact of cytokines on clinical outcome in malaria have identified TNF, IFN-γ, IL-1β, IL-6, IL-10, IL-12, transforming growth factor β and IP-10 as important mediators, but data on IL-8in this setting are more limited." (PMID 25503583, 2014). "Children also had higher IL-12 (P = 0.0001), IL-4 (P = 0.003), IL-1β (P = 0.024) and TNF (P = 0.006) levels compared to malaria-exposed adults." (PMID 23437061, 2013). "On the other hand, upon stimulation with LPS or Pam, high levels of IL-1β, IL-6, and TNF-α were produced by monocytes from malaria patients." (PMID 22745844, 2012). "IL-1β, TNF-α, and IL-12 were previously shown to play important roles in the pathophysiology of malaria and its cerebral form." (PMID 23300448, 2012). "While cytokines such as IL-6, IL-1β, and TNF-α have been extensively studied in relation to malaria severity, the role of IL-2 in immune regulation, T cell activation, and its potential dual contributions to both protective and pathogenic responses remain less well understood." (PMID 41194029, 2025). "In addition, malaria status predicted TNF‐α, IFN‐ɣ, IL‐1β, IL‐6, GM‐CSF and IL‐10 levels, whiles anemia severity predicted only IL‐3, IL‐10 and TGF‐β levels." (PMID 39240033, 2024). "Neither in our study nor these other studies of uncomplicated malaria were IL-1β levels increased in plasma." (PMID 38890271, 2024). "Malaria‐infected children had higher tumor necrosis factor alpha (TNF‐α) (p < .001), interferon‐gamma (IFN‐ɣ) (p < .001), interleukin (IL)‐1β (p < .001), IL‐6 (p < .001), granulocyte macrophage‐colony stimulating factor (GM‐CSF) (p < .001), and IL‐10 (p < .001) levels than controls." (PMID 39240033, 2024). "In malaria patients, caspase-1, caspase-4, caspase-8 and GSDMD are activated in monocytes, which may contribute to the overall increased levels of IL-1β and immunopathogenesis during P. vivax and P. falciparum infections." (PMID 39548522, 2024). "Additionally, to prevent severe malaria, IL-4 and IL-10 can directly downregulate IL-6, TNF-α, and IL-1β." (PMID 35820892, 2022). "During malaria, AIM2 and NLRP3-induced CASP1-dependent inflammasome signaling induces the release of IL-1β in pDCs and activates IL-1 signaling, which induces negative regulator SOCS1 in a MyD88-TRAF3-IRF3-dependent manner and inhibits MyD88-IRF7-dependent type I IFN signaling in pDCs." (PMID 36214572, 2022). "Using monocyte-derived macrophages from malaria-naïve individuals, it was reported that phagocytosis of antibody-opsonized IEs resulted in the secretion of TNF and IL-1β, with the latter occurring due to the activation of inflammasome following FcγR engagement." (PMID 34271941, 2021). "The second cluster of markers was composed by IFN-γ, creatinine, IL-1β, direct and indirect bilirubin, CXCL10 and IL-10, with heightened MDP values being observed in both the group of individuals with either asymptomatic or symptomatic malaria." (PMID 34727121, 2021). "Similar to responses seen with DCs from malaria-naïve US donors, mDCs obtained from Malians did not secrete significant amounts of the inflammatory cytokines IL-1β, IL-6 or TNF." (PMID 33407502, 2021). "Stimulation of monocytes from malaria-naïve individuals with antibody-opsonized IEs and purified parasite DNA-containing immune complexes can activate signalling pathways that lead to the production of pro-inflammatory cytokines, TNF and IL-1β." (PMID 34271941, 2021).
malaria (continued). "However, in these experiments M2 macrophages increased production of the pyrogenic cytokines IL-1β, IL-6 and TNF, and malaria-specific opsonising antibodies have been directly shown to promote inflammation in human macrophages." (PMID 33752799, 2021). "Serum levels of IL1-β, IL-6, CXCL1 and MCP-1 were evaluated to determine whether gestational malaria induced a systemic inflammatory response." (PMID 31391498, 2019). "In women with Malaria+CHB, correlation analysis showed significant negative association of the pro-inflammatory cytokines responses with malaria parasitemia [IL-1β (P<0." (PMID 31002731, 2019). "Also, elevated levels of TGF-β, TNF-α, IL-10, and IL-1β were found in cerebral malaria, while IL-2, IFN-γ, IL-5, IL-6, and IL-12 were only increased in mild malaria." (PMID 31878288, 2019). "Similarly, the Malaria+CHB group had significantly elevated pro-inflammatory cytokines, including tumour necrosis factor alpha (TNF-α), interleukin (IL)-1β, and IL-6 [P<0." (PMID 31002731, 2019). "A recent RNA-seq study of naïve and malaria-experienced Colombian volunteers who underwent CHMI with P. vivax also found no differential response in the fever-inducing inflammatory cytokines IL-1β, IL-6, IL-8 and TNF between naïve and malaria-experienced individuals at the time of diagnosis." (PMID 27506615, 2016). "Severe malaria patients exhibit high levels of serum pro-inflammatory cytokines (TNF, IL-1β, IL-6, IL-8, IL-12, IFNγ) and chemokines (CCL2, CCL5, CXCL9, CXCL10), and lower levels of regulatory cytokines (IL-10, TGFβ, PGE2) compared to those with mild and asymptomatic malaria." (PMID 27792766, 2016). "Surprisingly, in Odisha patients, IL-1β levels decreased with disease severity and were highest in severe malaria patients with no brain injury." (PMID 26602091, 2015). "Moreover, levels of IL-1β and TNF were higher in children compared to malaria-exposed adults during acute infection despite having a trend to lower parasite density than malaria-exposed adults mounting a higher antibody response to infection." (PMID 23437061, 2013). "The inflammatory condition of malaria is charcterised by free radical generation, activation of phospholipase activity resulting in generation of eicosanoids such as prostaglandins and other cytokines (TNF, IFN-γ, and IL-1β)." (PMID 23970953, 2013). "Kaplan-Meier curves indicate that children with high cord levels of IL-1β (but not TNF-α) are protected against severe malaria." (PMID 24130857, 2013). "Nlrp3 can however influence experimental cerebral malaria independently of caspase-1 and IL-1β, suggesting a non-classical role for Nlrp3 in malaria immunopathology." (PMID 23405174, 2013). "Conversely, the absence of NLRP3 or IL-1β resulted in increased survival of the malaria strain P. chabaudi adami DS, indicating that NLRP3 promotes malaria pathology." (PMID 24098823, 2013). "Monocytes produced high levels of IL-1β, IL-6 and TNF-α during acute malaria." (PMID 22745844, 2012). "This study found an association of iron deficiency anaemia with slightly reduced concentrations of IL-1β, IFN-γ and TNF in children without malaria but an increment in children with malaria infection." (PMID 20546583, 2010). "The significantly increased IL-10 and variable alteration in levels of TNF and IL-1β in both malaria-negative and malaria-positive subjects with magnesium deficiency may explain the imbalance in cytokine production as a result of magnesium deficiency modulated by malaria status." (PMID 20470442, 2010). "Genotypes of IL1B -31C>T and TNFA -308G>A in Thai malaria patients." (PMID 16098232, 2005). "Second, heme, a marker of hemolysis or extensive cell damage, activates the NLRP3 inflammasome and promotes IL-1β synthesis in macrophages by inducing Syk and NADPH oxidase-2 activation, mitochondrial ROS production, and potassium efflux, which play critical roles in malaria pathogenesis." (PMID 39548522, 2024).
malaria (continued). "This study found increased plasma levels of proinflammatory cytokines: TNF‐α, IFN‐ɣ, IL‐1β, IL‐6, and GM‐CSF, and the anti‐inflammatory cytokine IL‐10 in malaria‐infected children than the controls without malaria, and the levels were higher in participants with high parasitemia." (PMID 39240033, 2024). "Among both children less than 5 years, and those from 5 to 12 years, TNF‐α (p < .001), IFN‐ɣ (p < .001), IL‐1β (p < .001), IL‐6 (p < .001), GM‐CSF (p < .001), and IL‐10 (p < .001) levels were elevated in the participants with malaria compared with the apparently healthy children without malaria." (PMID 39240033, 2024). "However, in a human and murine study of infection using peripheral blood mononuclear cells, malaria induced the assembly of ASC, NLRP3 and NLRP12 inflammasomes jointly and promoted cleavage of procaspase-1, leading to IL-1β and hypersensitivity to bacterial superinfection." (PMID 38343435, 2023). "The engaged immune cells release inflammatory factors, such as pro-inflammatory cytokines/chemokines (e.g. IL-1β, TNF-α, Il-12, IL-10, Il-6), nitric oxide (NO) and reactive oxygen species (ROS) that drive the inflammatory response and lead to the fever-like symptoms observed in malaria patients." (PMID 37350957, 2023). "However, IL-1β levels were not different between patients with uncomplicated malaria and healthy controls." (PMID 36309676, 2022). "However, for the malaria group, four distinct correlation patterns were observed; first pattern (CCL4, CCL2, CCL3, IL12 and IL2), second pattern (IL-17A, IL-1β, CCL11, IL4), third pattern (IL5, IL7, IL13), and fourth pattern (IL1RA, CXCL10, TNFα, IL2R, CXCL9, IL6)." (PMID 35811678, 2022). "However, meta-analysis results demonstrating differences in mean IL-1β levels between patients with uncomplicated malaria and healthy controls were not robust." (PMID 36309676, 2022). "Hence, we revisited this question to evaluate the contribution of the noncanonical pathway on IL-1β release during malaria." (PMID 32929083, 2020). "Elevated levels of IL‐1β lead to inflammatory events such as fever, increased circulating neutrophils, upregulation of surface markers in cells, extensive nitric oxide production, and elevated levels of CRP and inflammatory cytokines, which are all common in malaria." (PMID 31265218, 2019). "Previous reports have identified that Plasmodium infection activates the inflammasome in human patients; however, studies in vitro needed an additional exogenous signal 1 for the production of IL‐1β that was added in the form of LPS, which is a bacterial product not present during malaria." (PMID 31265218, 2019). "Similarly, low levels of IL-1β and TNF-α have been found in patients with severe malaria." (PMID 30800644, 2019). "For instance, increased plasma levels of pro-inflammatory tumour necrosis factor (TNF), interferon-gamma (IFN-γ), and interleukin-1 beta (IL-1β), as well as decreased levels of anti-inflammatory cytokines, such as IL-10 and transforming growth factor beta 1 (TGF-β1), are hallmarks of severe malaria." (PMID 27357958, 2016). "In addition, malaria antigens have been reported to activate macrophages and monocytes to produce various cytokines, such as tumour necrosis factor (TNF)-alpha and interleukin-1 beta." (PMID 25879828, 2015). "We measured plasma levels of soluble UA and inflammatory cytokines and chemokines (IL-6, IL-10, sTNFRII, MCP-1, IL-8, TNFα, IP-10, IFNγ, GM-CSF, IL-1β) in 470 Malian children presenting with uncomplicated malaria (UM), non-cerebral severe malaria (NCSM) or cerebral malaria (CM)." (PMID 23071567, 2012). "Despite the fact that neutrophils are an important source of cytokines, we found that except for IL-8 (CXCL8), the neutrophils from malaria patients produced none or very small amounts of pro-inflammatory cytokines (i.e., IL-1β, IL-6, and TNF-αin response to TLR agonists." (PMID 22745844, 2012).